STRCP1 (stereocilin pseudogene 1)
Synonyms: formerly STRCP
Gene: Transcribed unprocessed pseudogene on chromosome 15 (43,699,488 to 43,718,184, reverse strand). Ensembl gene ENSG00000166763.
Subcellular location: Secreted